COL22A1 (collagen type XXII alpha 1 chain)
Description:
Acts as a cell adhesion ligand for skin epithelial cells and fibroblasts.
Tractability: Antibody: its Gene Ontology location is reachable by antibodies, with high confidence; UniProt places it where antibodies can reach, with medium confidence; UniProt predicts a signal peptide or a membrane-spanning region.
Gene: Protein-coding gene on chromosome 8 (138,588,235 to 138,914,063, reverse strand). Ensembl gene ENSG00000169436.
Subcellular location: Secreted, extracellular space, extracellular matrix; Cytoplasm
Subcellular location (Human Protein Atlas): Vesicles; Endoplasmic reticulum; Predicted to be secreted
Pathways (Reactome):
Extracellular matrix organization: Collagen biosynthesis and modifying enzymes; Collagen chain trimerization
Gene Ontology:
Molecular function: extracellular matrix structural constituent conferring tensile strength
Biological process: extracellular matrix organization
Cellular component: basement membrane; collagen type XXII trimer; endoplasmic reticulum lumen; extracellular region; cytoplasm
Genetic constraint (gnomAD): Loss-of-function variants: 165 observed, 186.85 expected, observed/expected ratio (o/e) 0.88, 90% interval 0.78 to 1. The upper end of that interval is the gene's LOEUF score, 1, which puts it in group 4 of 6, group 1 being the genes least tolerant of losing a copy. Missense variants: 1,932 observed, 1,846.9 expected, observed/expected ratio (o/e) 1.05, 90% interval 1.01 to 1.09. Synonymous variants: 787 observed, 681.73 expected, observed/expected ratio (o/e) 1.15, 90% interval 1.09 to 1.22.
Homologues: Orthologues: chimpanzee COL22A1 (97% identical), macaque COL22A1 (96% identical), dog COL22A1 (89% identical), guinea pig COL22A1 (86% identical), pig COL22A1 (86% identical), tropical clawed frog col22a1 (67% identical), Caenorhabditis elegans col-87 (6% identical). Paralogues in human: COL5A1 (33% identical), COL11A1 (32% identical), COL11A2 (31% identical), COL2A1 (31% identical), COL5A3 (30% identical), COL4A5 (30% identical), COL1A1 (30% identical), COL4A1 (30% identical), COL4A6 (29% identical), COL3A1 (29% identical), COL4A2 (29% identical), COL5A2 (29% identical), and 25 more.